BDKRB2 (bradykinin receptor B2)
Diseases named in the same sentence as BDKRB2 in open-access papers (continued):
Sharing a sentence is not in itself a finding about the gene and the disease.
Anxiety (3 papers, 2019 to 2024). Intense feelings of nervousness, tension, or panic often arise in response to interpersonal stresses. "Our finding that especially BDKRB2 levels were altered after acute and chronic stress, major risk factors for anxiety disorders, encouraged us to test whether antagonists of BDKRB1 or BDKRB2 affect anxiety-like behaviour in mice." (PMID 31857655, 2019). "Furthermore, we tested the effect of BDKRB1 and BDKRB2 antagonists on mouse anxiety-like behaviour and physiological stress responses." (PMID 31857655, 2019). "Bdkrb2 gene was upregulated in both stress-susceptible and resilient mice, which may indicate a general stress effect rather than an anxiety effect." (PMID 31857655, 2019). "Since acute or chronic stress did not affect gene or protein expression of BDKRB1, nor did the BDKRB1 receptor antagonist influence anxiety-like behaviour, we concentrated on the BDKRB2." (PMID 31857655, 2019). "We also tested if blocking BDKRB2 with WIN 64338 affects stress-induced hyperthermia, another model of anxiety-like behaviour not dependent on spontaneous activity." (PMID 31857655, 2019).
asthma (3 papers, 2015 to 2021). "Another gene, Bdkrb2, was also linked to the asthma treatment." (PMID 34285702, 2021). "In this study, Bdkrb2 was significantly upregulated in the asthma rats after HCZP treatment, suggesting that HCZP might exert therapeutic effects on asthma by affecting the expression of bradykinins." (PMID 34285702, 2021).
astrocytoma (3 papers, 2010 to 2022). "Transcripts exhibiting significant under expression in trisomic BG01V APCs and CCF-STTG1 astrocytoma cells relative to diploid H9 APCs include several markers of normal differentiated astrocytes, including TRPA1, GABRA2, BDNF, BDKRB1 and BDKRB2." (PMID 20423517, 2010).
osteoarthritis (3 papers, 2014 to 2025). A noninflammatory degenerative joint disease occurring chiefly in older persons, characterized by degeneration of the articular cartilage, hypertrophy of bone at the margins and changes in the synovial membrane. "The +9/−9 bp polymorphism in its gene influences BDKRB2 expression levels in osteoarthritis patients, subsequently affecting inflammatory responses and disease severity." (PMID 40564415, 2025).
allergic disease (2 papers, 2015 to 2021). An immune response that occurs following re-exposure to an innocuous antigen, and that requires the presence of existing antibodies against that antigen. "Bradykinin can expand blood vessels, increase blood vessel permeability, induce bronchospasm, and promote bronchial contraction and other allergic reactions by binding to bradykinin receptors (BDKRB2) on the surfaces of target cells." (PMID 33732214, 2021).
atherosclerosis (2 papers, 2019 to 2020). A disease characterized by the build-up of fatty material and calcium deposition in the arterial wall resulting in partial or complete occlusion of the arterial lumen. "We found that transgenic B2 receptor expression enhanced atherosclerotic plaque formation in the aorta of ApoE–/– mice whereas Bdkrb2 deficiency retarded the development of atherosclerosis." (PMID 30847343, 2019). "To study the role of the B2 bradykinin receptor (Bdkrb2) in atherosclerosis, we used (i) ApoE–/– mice with endogenously expressed Bdkrb2, (ii) ApoE–/– mice with Bdkrb2 deficiency, and (iii) ApoE–/– mice with moderately increased transgenic BDKRB2 expression level." (PMID 30847343, 2019). "Together our data show that the B2 bradykinin receptor is atherogenic, and the atherosclerosis-promoting function of BDKRB2 is partially caused by decreased aortic BH4 levels, which could account for eNOS uncoupling and further enhancement of ROS generation." (PMID 30847343, 2019). "The role of Bdkrb2 in atherosclerosis was studied in ApoE-deficient mice, which were either Bdkrb2-deficient, or had moderately increased aortic B2 bradykinin receptor protein levels induced by transgenic BDKRB2 expression under control of the ubiquitous CMV promoter." (PMID 30847343, 2019). "BH4 depletion contributes to the atherogenic activity of the B2 bradykinin receptor because supplementation with BH4 was sufficient to inhibit aortic ROS and retard atherosclerosis progression triggered by transgenic BDKRB2 expression." (PMID 30847343, 2019). "These experiments show that BH4 supplementation is capable to counteract the atherosclerosis-promoting ROS generation in Tg-B2++ApoE–/– mice with transgenic BDKRB2 expression." (PMID 30847343, 2019). "In search for pathomechanisms of atherosclerosis, we investigated the impact of the B2 bradykinin receptor, Bdkrb2, on atherosclerotic lesion formation, because to date it is not clear whether the B2 bradykinin receptor is atheroprotective or atherogenic." (PMID 30847343, 2019). "However, the atherosclerosis-lowering potential of ACE inhibition does not necessarily rely on bradykinin-stimulated Bdkrb2 activation, e.g., when there is no activation of the (brady)kinin-generating kallikrein system." (PMID 30847343, 2019).
brain glioma (2 papers, 2022 to 2024). A malignant glioma that involves the brain. "Increased expression of kinin receptors BDKRB1 and BDKRB2 in brain gliomas, depending on the degree of malignancy, suggests the involvement of kinins and their receptors in the disease’s pathogenesis." (PMID 38254732, 2024).
epilepsy (2 papers, 2024 to 2025). A brain disorder characterized by episodes of abnormally increased neuronal discharge resulting in transient episodes of sensory or motor neurological dysfunction, or psychic dysfunction. "The disparity in the transcriptional activity of BDKRB1 and BDKRB2 may be explained by the “cross-talk” between B2R and B1R, as previously demonstrated in a rat model of kindling-induced epilepsy." (PMID 38254732, 2024).
gout (2 papers, 2022 to 2023). A condition characterized by painful swelling of the joints, which is caused by deposition of urate crystals. "Genetic disruption of the bradykinin receptors B1 (BDKRB1) and B2 (BDKRB2) decreases inflammatory sensitivity in a variety of disease‐specific models, including the multiple sclerosis model experimental autoimmune encephalomyelitides and a gout model induced by monosodium urate injection." (PMID 35760453, 2022).
malignant glioma (2 papers, 2021 to 2022). A grade III or grade IV glioma arising from the central nervous system. "Downregulation of miR-130b-5p complemented by increased level of its target mRNA BDKRB2 which is associated with patient survival rate and more malignant glioma phenotypes." (PMID 36354672, 2022).
panic disorder (2 papers, 2022). An anxiety disorder characterized by multiple unexpected panic attacks with persistent concern of recurring attacks. "Remarkably, a functional SNP, rs945032, located in the promoter region of BDKRB2, was associated with three disorders (panic disorder, substance abuse, and bipolar disorder)." (PMID 35893041, 2022). "Some researchers have tried to determine the genetic basis of panic disorder, and some suggestive associations have been observed in several loci, such as BDKRB2 or NPY5R, with this disorder." (PMID 36231907, 2022). "Gratacòs and colleagues studied the role of rs945032 (BDKRB2); this SNP is associated with three diagnoses, panic disorder, substance abuse, and bipolar disorder, remaining significant after correction in the case of panic disorder." (PMID 35893041, 2022).
parasite infection (2 papers, 2007 to 2015). "Interestingly, it was observed that cruzipain is able to release kinin activity from secluded spaces, which could then activate the bradykinin receptor B2, facilitating parasite infection." (PMID 25938232, 2015).
renal fibrosis (2 papers, 2021). A final common manifestation of a wide variety of chronic kidney diseases characterized by glomerulosclerosis and tubulointerstitial fibrosis. "In contrast, BDKRB2 activation protected against renal fibrosis via the PA/MMP-2 cascade by increasing ECM degradation." (PMID 34830489, 2021).
Sepsis (2 papers, 2019 to 2025). Sepsis is defined as life-threatening organ dysfunction caused by a dysregulated host response to infection. "This study demonstrated that the genetic deletion of Bdkrb2 had no significant impact on sepsis induced by cecal ligation and puncture (CLP) compared to wild-type (WT) mice." (PMID 41355798, 2025).
anxiety disorder (1 paper, 2019). A category of psychiatric disorders which are characterized by anxious feelings or fear often accompanied by physical symptoms associated with anxiety. "In human genetic association analysis, variants in genes for the bradykinin precursor (KNG1) and the bradykinin receptors (BDKRB1 and BDKRB2) were associated with anxiety disorders (p < 0.05)." (PMID 31857655, 2019). "BDKRB2 protein levels were decreased in the mouse hippocampus by acute stress while Bdkrb2 gene expression levels were increased after chronic psychosocial stress, a major risk factor for anxiety disorders." (PMID 31857655, 2019). "Of the 21 analysed KNG1 SNPs, 17 BDKRB1 SNPs, and 20 BDKRB2 SNPs, 5, 8, and 1 associated with anxiety disorders at the nominal p < 0.05 level, respectively." (PMID 31857655, 2019). "Therefore, we systematically selected a comprehensive set of SNPs from the KNG1, BDKRB1, and BDKRB2 genes and genotyped them in a well-characterized Finnish anxiety disorder case-control sample, representative of the Finnish population." (PMID 31857655, 2019). "To investigate whether genetic variants in the KKS genes associate with anxiety disorders, we genotyped SNPs from KNG1, BDKRB1, and BDKRB2 in anxiety disorder cases (n = 321) and carefully matched controls (n = 653) from the Finnish population-based Health 2000 Survey." (PMID 31857655, 2019).
candidiasis (1 paper, 2016). Infection with the organism Candida. "Moreover, the relative contributions of Bdkrb1 and Bdkrb2 in renal defense against candidiasis need to be determined, which is possible with specific knockout mouse strains." (PMID 27814401, 2016).
cardiomyopathy (1 paper, 2021). A disease of the heart muscle or myocardium proper. "Results of the current study showed that MKI67 induces cardiomyopathy, and BDKRB2 inhibits the disorder." (PMID 34236536, 2021). "In contrast, our results showed that BDKRB2 genes inhibit cardiomyopathy." (PMID 34236536, 2021).
Cough (1 paper, 2023). A sudden, audible expulsion of air from the lungs through a partially closed glottis, preceded by inhalation. "Nonetheless, the same study reported a different association between cough incidence and a nine-base-pair deletion in the BDKRB2 first exon, referred to as the B2 -9 allele." (PMID 38108069, 2023). "One of the earliest studies on this topic investigated the association of variants in the bradykinin receptor B2 (BDKRB2) gene with ACEIs-cough." (PMID 38108069, 2023).
deep venous thrombosis (1 paper, 2018). "Considering the potential relationship between BDKRB2 and thrombosis, the underlying association and mechanism between BDKRB2 variants and DVT are worth investigation." (PMID 30478260, 2018).
dementia (1 paper, 2015). Loss of intellectual abilities interfering with an individual's social and occupational functions. "Previous studies support the proposed effectiveness of an action on BDKRB2 for the treatment of dementia, demonstrating the ability of a BDKRB2 antagonist (HOE 140) in reversing the spatial learning and memory deficits induced by Aβ peptide in an animal model of Alzheimer’s disease." (PMID 26154857, 2015).
liver fibrosis (1 paper, 2021). "However, our data showed that bradykinin receptors, especially Bdkrb2 mRNA level, are positively associated with liver fibrosis, implicating a potential role for these receptors in liver injury." (PMID 34566641, 2021). "The thrombin receptors, protease-activated receptors (PAR) 1 and 2, and the bradykinin receptor, beta 2 (BDKRB2), are upregulated in liver fibrosis with a possible involvement of the latter and its ligand, bradykinin (BK) in fibrotic resolution." (PMID 34566641, 2021). "This development among Kng1, Bdkrb1, and Bdkrb2 gene expressions, and myofibroblast activators and chronic liver injury creates a new direction in the study of liver fibrosis and its resolution." (PMID 34566641, 2021). "Last, the gene expression of Bdkrb2 was significantly induced in response to chronic liver injury in C57BL6/J mice and was positively correlated with the progression of liver fibrosis." (PMID 34566641, 2021).
myopia (1 paper, 2018). "BDKRB2 has frequently been associated with brain edema, fluid leakage, signaling by GPCR and regulation of actin cytoskeleton and potentially may allow fluids to leak into the retina/vitreous as seen in pathological myopia (Francisco, Salvador & Amparo, 2015)." (PMID 29967729, 2018).
pulmonary hypertension (1 paper, 2009). Increased pressure within the pulmonary circulation due to lung or heart disorder. "In the pulmonary circulation, Taraseviciene-Stewart and colleagues examined the influence of a long-acting BDKRB2 agonist on pulmonary artery pressure in rats with severe pulmonary hypertension." (PMID 20957051, 2009).
tumor (31 papers, 2007 to 2025). "Further analysis of receptor-ligand interactions highlighted the roles of KNG1_BDKRB2 and NRG1_ERBB4 signaling in promoting tumor aggression, suggesting potential therapeutic targets." (PMID 40969325, 2025). "BDKRB2 can promote tumor progression through multiple pathways, and its expression level is often positively correlated with the malignant characteristics of tumor." (PMID 40224547, 2025). "Across different malignancies, via activating BDKRB2, BK promotes tumor progression through various pathways." (PMID 33686021, 2021). "BDKRB2 expression was also significantly decreased in the xenograft tumor tissues of shNMI groups tumors compared with that of control." (PMID 28077802, 2017). "A growing number of studies had investigated that BDKRB2 played a crucial role in bradykinin-regulating tumor progression." (PMID 28077802, 2017). "BDKRB2 promotes tumor growth and invasion, increases blood supply and other survival signals." (PMID 37056339, 2023). "This suggests that KNG1_BDKRB2 may be involved in tumor progression." (PMID 40969325, 2025). "BDKRB2 can promote angiogenesis by increasing vascular permeability and upregulating vascular endothelial growth factor (VEGF) and can also promote tumor cell migration and invasion through TRPM7, MMP2, endothelin-1, and ERK signaling pathways." (PMID 40224547, 2025). "There is a fine regulation of GBM cell proliferation, since we see, that the upregulation of the BDKRB2 and TGM2 mRNAs leads to stimulation of the EMT, which is necessary for tumor progression migration and metastasis." (PMID 36354672, 2022). "In conclusion, our results show that NMI is a novel promotor of tumor growth, invasion and metastasis of HCC by inducing its downstream target BDKRB2 expression and activating MAPK/ERK signaling pathway." (PMID 28077802, 2017). "Moreover, in vitro and in vivo assays showed that NMI significantly promoted tumor proliferation, invasion, and metastasis of HCC by inducing its downstream target BDKRB2 expression and activator of MAPK/ERK signaling pathway." (PMID 28077802, 2017).
infection (23 papers, 2007 to 2025). The state of being infected such as from the introduction of a foreign agent such as serum, vaccine, antigenic substance or organism. "By contrast, stimulation of the bradykinin-receptor B2 (BDKRB2) is decreased due to the inhibition of cathepsin L, a kininogenase involved in bradykinin production and present at the infection site." (PMID 36143272, 2022).
cancer (16 papers, 2012 to 2024). A tumor composed of atypical neoplastic, often pleomorphic cells that invade other tissues. "Moreover, several studies sought to investigate the correlation between BDKRB2 expression and clinical characterization and have concluded relatively consistent results across different cancers." (PMID 33686021, 2021). "Other target genes in our study including ADCY1, BCL2, BDKRB2, CALM1, and CCND1 have been proved to play important roles in multiple pathways of cancer progression." (PMID 31775867, 2019).
cardiovascular diseases (7 papers, 2010 to 2022). "An abnormal gene structure of BDKRB2 would contribute to EH and other cardiovascular diseases, suggesting that it is a candidate gene for EH." (PMID 22900090, 2012). "Polymorphic loci of four genes whose products are involved in blood pressure control (ACE, BDKRB2, NOS3 and PPARGC1A) can be used in martial arts not only to determine predisposition to cardiovascular disease but also to predispose to the development of speed and power qualities and endurance." (PMID 36140844, 2022). "For those with the AT1R A1166C AA genotype, individuals with the BDKRB2 exon 1 I/D +9/+9 genotype had a significantly lower hazard of cardiovascular disease as compared to those who carried either the BDKRB2 exon 1 I/D −9/+9 or −9/−9 genotypes (adjusted HR = 0.45, 95% CI: 0.24–0.82)." (PMID 20856803, 2010). "The present study suggests possible interactions between the ACE I/D and PAI-1 4G/5G polymorphisms, the BDKRB2 C181T and ACE I/D polymorphisms, the BDKRB2 exon 1 I/D and AT1R A1166C polymorphisms, and the BDKRB2 C58T and AT1R A1166C polymorphisms on the risk of cardiovascular disease." (PMID 20856803, 2010). "For those with the AT1R A1166C AA genotype, individuals with the BDKRB2 C58T TT or BDKRB2 C58T CT genotypes had a significantly higher hazard of cardiovascular disease as compared to those who carried the BDKRB2 C58T CC genotype (adjusted HR = 1.67, 95% CI: 1.04–2.70)." (PMID 20856803, 2010).
inflammation (2 papers, 2014 to 2022). Aberrant reaction of the microcirculation characterized by movement of fluid and leukocytes from the blood into extravascular tissues. "Bradykinin has been implicated in the pathogenesis of renal inflammation, whereas the role of its receptor 2 (B2RBK; also known as BDKRB2) in FSGS has not been studied." (PMID 24742784, 2014).
BDKRB2 also shares sentences with these, for which no sentence is quoted: Arthritis (6 papers); Nephropathy (6); preeclampsia (6); lung carcinoma (5); acute respiratory distress syndrome (4); diabetic nephropathy (4); myocardial infarction (4); Obesity (4); brain ischemia (3); cardiac hypertrophy (3); head and neck squamous cell carcinoma (3); hepatocellular carcinoma (3); ischemia (3); ischemic stroke (3); lupus (3); myocardial ischemia (3); amyloid (2); autoimmune disease (2); cervical cancer (2); cognitive deficit (2); edema (2); Insulin resistance (2); multiple sclerosis (2); pulmonary edema (2); rheumatoid arthritis (2); sarcopenia (2); type 2 diabetes (2); acute myocardial infarction (1); allergic rhinitis (1); Allergy (1).
A further 76 diseases each share a sentence with BDKRB2 in 1 paper.